ATAD5 (ATPase family AAA domain containing 5)
Description:
Has an important role in DNA replication and in maintaining genome integrity during replication stress. Involved in a RAD9A-related damage checkpoint, a pathway that is important in determining whether DNA damage is compatible with cell survival or whether it requires cell elimination by apoptosis. Modulates the RAD9A interaction with BCL2 and thereby induces DNA damage-induced apoptosis. Promotes PCNA deubiquitination by recruiting the ubiquitin-specific protease 1 (USP1) and WDR48 thereby down-regulating the error-prone damage bypass pathway. As component of the ATAD5 RFC-like complex, regulates the function of the DNA polymerase processivity factor PCNA by unloading the ring-shaped PCNA homotrimer from DNA after replication during the S phase of the cell cycle. This seems to be dependent on its ATPase activity. Plays important roles in restarting stalled replication forks under replication stress, by unloading the PCNA homotrimer from DNA and recruiting RAD51 possibly through an ATR-dependent manner. Ultimately this enables replication fork regression, breakage, and eventual fork restart. Both the PCNA unloading activity and the interaction with WDR48 are required to efficiently recruit RAD51 to stalled replication forks. Promotes the generation of MUS81-mediated single-stranded DNA-associated breaks in response to replication stress, which is an alternative pathway to restart stalled/regressed replication forks.
Synonyms: C17orf41; Elg1; FRAG1; FLJ12735
Tractability: Small molecule: a structure with a bound ligand is known. PROTAC: UniProt records ubiquitination sites on it; ubiquitination databases record sites on it.
Chemical probes: ML367
Gene: Protein-coding gene on chromosome 17 (30,831,966 to 30,895,869, forward strand). Ensembl gene ENSG00000176208.
Subcellular location: Nucleus
Subcellular location (Human Protein Atlas): Nucleoplasm; Centriolar satellite; Cytokinetic bridge; Cytosol
Gene Ontology:
Molecular function: DNA clamp unloader activity; protein binding; DNA binding; ATP binding; ATP hydrolysis activity
Biological process: positive regulation of cell cycle G2/M phase transition; positive regulation of DNA replication; cell population proliferation; nuclear DNA replication; positive regulation of DNA metabolic process; regulation of cell cycle phase transition
Cellular component: Elg1 RFC-like complex; nucleus
Genetic constraint (gnomAD): Loss-of-function variants: 47 observed, 143.68 expected, observed/expected ratio (o/e) 0.33, 90% interval 0.26 to 0.42. The upper end of that interval is the gene's LOEUF score, 0.42, which puts it in group 1 of 6, group 1 being the genes least tolerant of losing a copy. Missense variants: 1,611 observed, 1,907 expected, observed/expected ratio (o/e) 0.84, 90% interval 0.81 to 0.88. Synonymous variants: 600 observed, 660.01 expected, observed/expected ratio (o/e) 0.91, 90% interval 0.85 to 0.97.
Homologues: Orthologues: chimpanzee ATAD5 (99% identical), macaque ATAD5 (93% identical), dog ATAD5 (79% identical), pig ATAD5 (78% identical), rabbit ATAD5 (78% identical), guinea pig ATAD5 (75% identical), rat Atad5 (70% identical), mouse Atad5 (69% identical), tropical clawed frog atad5 (35% identical), zebrafish atad5a (32% identical), zebrafish atad5b (16% identical), Drosophila melanogaster elg1 (13% identical). Paralogues in human: CRLF3 (5% identical).
Diseases named in the same sentence as ATAD5 in open-access papers:
ATAD5 is named in the same sentence as 21 diseases in open-access papers, as found by Europe PMC text mining. Sharing a sentence is not in itself a finding about the gene and the disease. The quoted sentences say what the papers report.
ovarian carcinoma (6 papers, 2018 to 2024). A malignant neoplasm originating from the surface ovarian epithelium. "So far, heterozygous mutations in ATAD5 have been evidenced in endometrial, breast and ovarian cancers." (PMID 38448973, 2024). "In another study, the upregulation of Polθ and its positive correlation with expression of many DNA repair genes including TOPBP1, BLM, RAD54L, FANCI, BRCA1, FANCD2, ATAD5 was reported in HR-deficient epithelial ovarian cancer cells." (PMID 34762643, 2021). "Studies have designated ATAD5 as a key biomarker for ovarian cancer; deficient ATAD5 activity is linked to impaired PCNA unloading from the DNA strand and increased genomic instability." (PMID 33023096, 2020). "Moreover, ATAD5 is a tumor suppressor; haploinsufficient mice display genomic instability and are cancer prone, and a genome-wide association study identified ATAD5 as an ovarian cancer susceptibility locus." (PMID 30889383, 2019). "The major phenotype of mice lacking ATAD5 is cancer predisposition, and indeed ATAD5 mutations are also proposed to contribute to human ovarian cancers." (PMID 30418970, 2018).
endometrial tumors (3 papers, 2011 to 2019). "In humans, somatic mutations in ATAD5 have been found in primary endometrial tumors, and ATAD5 was identified as a susceptibility locus for invasive epithelial ovarian cancer." (PMID 31114918, 2019). "Other examples include TSC2, where mutations have been linked to the development of hamartomas in multiple organs; and ATAD5, the somatic mutations of which were identified in endometrial tumors." (PMID 27150584, 2016). "Overall, we identified 11 somatic mutations in the ATAD5 gene in 4.6% (5 of 108) of endometrial tumors." (PMID 21901109, 2011). "Consistent with a role for Atad5 in suppressing tumorigenesis, we also identified somatic mutations of ATAD5 in 4.6% of sporadic human endometrial tumors, including two nonsense mutations that resulted in loss of proper ATAD5 function." (PMID 21901109, 2011). "In a subset of sporadic human endometrial tumors, we identified heterozygous loss-of-function somatic mutations in the ATAD5 gene, consistent with the role of mouse Atad5 in suppressing tumorigenesis." (PMID 21901109, 2011). "Somatic mutations of ATAD5 were identified in primary human endometrial tumors." (PMID 21901109, 2011). "Since haploinsufficiency for Atad5 leads to cancer predisposition in our mouse model, we sought to determine whether the wild type ATAD5 allele is expressed in the human endometrial tumor (T51) with the ATAD5-R1414X mutation." (PMID 21901109, 2011). "To test whether the somatic ATAD5 mutations we observed in human endometrial tumors encode loss-of function proteins, we compared the functional properties of wild type and mutant (P91H, P1516T, S1589C, E723X, and R1414X) forms of ATAD5." (PMID 21901109, 2011). "To test this hypothesis we searched for somatic ATAD5 mutations among a series of sporadic human endometrial tumors." (PMID 21901109, 2011). "In addition, human endometrial tumors carrying ATAD5-R1414X mutation expressed both the wild type and mutant alleles." (PMID 21901109, 2011). "We resequenced all coding exons of ATAD5 from 108 primary endometrial tumors, consisting of 66 NEECs and 42 EECs." (PMID 21901109, 2011).
sarcoma (3 papers, 2011 to 2019). A usually aggressive malignant neoplasm of the soft tissue or bone. "Embryonic fibroblasts from more than 90% of haploinsufficient Atad5+/m mice developed tumors such as sarcomas, carcinomas, and adenocarcinomas that exhibited high levels of genomic instability." (PMID 31652930, 2019). "In contrast, necropsy analyses revealed that Atad5+/m mice developed a variety of tumors in many tissues and cell types with a high incidence of adenocarcinomas and sarcomas." (PMID 21901109, 2011). "The predominance of adenocarcinomas and sarcomas observed in Atad5+/m mice is in stark contrast to the range of tumors observed in the 129/Sv strain used in this study." (PMID 21901109, 2011). "We next compared the gene expression profiles of one adenocarcinoma and one sarcoma from Atad5+/m mice with those of their surrounding tissues, by microarray analysis." (PMID 21901109, 2011). "We used array-comparative genome hybridization to determine the genomic copy number profiles of 2 adenomas and 2 sarcomas from the Atad5+/m mice." (PMID 21901109, 2011). "Importantly, 90% of haploinsufficient Atad5+/m mice developed tumors, including sarcomas, carcinomas, and adenocarcinomas, between 11 and 20 months of age." (PMID 21901109, 2011).
endometrial cancer (2 papers, 2011 to 2020). Primary or metastatic malignant neoplasm involving the endometrium (mucous membrane that lines the endometrial cavity). "We further show that somatic, loss-of-function mutations in ATAD5 are present in a subset of primary human endometrial cancers." (PMID 21901109, 2011). "In this report we have demonstrated the first somatic ATAD5 mutations in human cancer through a resequencing analysis of primary endometrial carcinomas." (PMID 21901109, 2011). "As Atad5 heterozygous mice are cancer-prone and as ATAD5 mutations have been identified in breast and endometrial cancers, our finding may open a path towards the therapy of these tumours." (PMID 32297953, 2020). "In this regard, it will be interesting, in future studies, to determine the extent to which the ATAD5 pathway is disrupted in sporadic endometrial cancer." (PMID 21901109, 2011). "We conclude that the truncated ATAD5-R1414X mutant protein is unstable and that it may contribute to endometrial cancer by a haploinsufficient mechanism." (PMID 21901109, 2011). "Although ATAD5 was mutated at low frequency in endometrial carcinomas, this is not unexpected in light of recent studies of whole exomes of breast, colorectal and pancreatic cancers." (PMID 21901109, 2011).
dysferlinopathy (1 paper, 2023). "Analysis of muscle transcripts from patients with dysferlinopathy identified 6 downregulated DEGs (RFC4, RFC5, ATAD5, TP53BP1, WDR48, and RAD17) related to the cellular response to DNA damage stimulus." (PMID 38125829, 2023).
inflammatory bowel disease (1 paper, 2025). A spectrum of small and large bowel inflammatory diseases of unknown etiology. "In particular, trichostatin A (TSA), a histone deacetylase inhibitor that targets ATAD5, has shown promise in reducing chronic inflammation and fibrosis in other disorders such as inflammatory bowel disease and hepatic ischemia-reperfusion damage." (PMID 40766329, 2025).
neurofibromatosis type 1 (1 paper, 2011). A clinically heterogeneous, neurocutaneous genetic disorder characterized by cafe-au-lait spots, iris Lisch nodules, axillary and inguinal freckling, and multiple neurofibromas. "Notably, there are studies suggesting a higher cancer incidence in approximately 5 to 10% of Neurofibromatosis type 1 patients who have a micro-deletion that includes NF1, ATAD5, and several other genes." (PMID 21901109, 2011).
Salmonella Infections (1 paper, 2024). Infections with bacteria of the genus SALMONELLA. "According to the present results, the downregulation of ATAD5 after Salmonella infection may indicate an impaired cell cycle and DNA replication in the intestine, and berberine may alleviate this obstruction." (PMID 39664055, 2024).
tumor (19 papers, 2011 to 2024). "Type-1 and type-2 deletions at the NF1 locus constitutively result in ATAD5 haploinsufficiency, which most probably constitutes an additional risk factor for genomic instability and tumour emergence." (PMID 38448973, 2024). "ATAD5 is considered to function as a tumor suppressor based on the tumor incidence in Atad5 heterozygote mutant mice and frequent mutations of the ATAD5 gene in patients with various types of cancer." (PMID 31844045, 2019). "The microarray analysis and quantitative PCR of mouse tumor samples showed that the wild type allele of Atad5 was retained and was expressed normally." (PMID 21901109, 2011). "One of the nonsense mutations (ATAD5-R1414X) occurred in an almost equivalent position to the insertion mutation within the Atad5 tumor-prone mouse described here." (PMID 21901109, 2011). "By sequencing RT-PCR products generated from purified populations of tumor cells obtained by laser capture microdissection, we observed expression of both the wild type and ATAD5-R1414X alleles." (PMID 21901109, 2011). "As concerted efforts to systematically sequence entire tumor exomes and genomes move forward rapidly, we predict that a wider spectrum of sporadic human tumors will harbor acquired somatic ATAD5 mutations." (PMID 21901109, 2011). "Moreover, the mammalian ortholog of Elg1 (ATAD5) is a tumor suppressor in mice and is associated with cancer in humans." (PMID 38427736, 2024). "Human ELG1/ATAD5 plays an essential role in maintaining genome stability and the gene coding for it acts as a tumor suppressor gene." (PMID 35708277, 2022). "It is still unclear which of the PCNA-regulating functions of ATAD5-RLC are important for its role as a tumor suppressor." (PMID 31844045, 2019). "Differential gene expression analysis revealed 3155 DEGs (differentially expressed genes), among which six AAA ATPase genes (TRIP13, CHTF18, RFC4, ATAD2, FIGNL2, ATAD5) were significantly overexpressed in tumor samples compared to levels in normal samples." (PMID 31533816, 2019). "Another tumour suppressor gene located within the NF1 microdeletion region is ATAD5 (ATPase family AAA domain–containing protein 5)." (PMID 28213670, 2017). "The requirement for Elg1 in genome maintenance is conserved in higher eukaryotes, since mice with reduced expression of ATAD5 (the mammalian ortholog of Elg1) exhibit genome instability and have a high tumor incidence." (PMID 27373149, 2016). "However, it is still unclear how the knockout phenotypes in mice, especially embryonic lethality and tumor incidence in ATAD5-knockout mice, are related to the molecular and cellular activities of these proteins." (PMID 33339954, 2020). "Here, we have provided another molecular mechanism that might explain the tumor-suppressive function of ATAD5." (PMID 31844045, 2019). "The mouse ortholog of ELG1 (ATAD5) is essential for life and acts as a tumor suppressor." (PMID 31186330, 2019). "Over-recruitment of PCNA-interacting proteins may disturb DNA replication and repair, potentially causing the defects observed in ATAD5 knockdown cells, which include chromosome instability and increased spontaneous DNA damage, as well as high tumor incidence in mice with reduced ATAD5 expression." (PMID 31114918, 2019). "In addition to the deletion of SUZ12 and ATAD5, hemizygosity forthe genes COPRS, UTP6 and RNF135 may alsocontribute to the increased tumour risk associated with NF1 microdeletions." (PMID 28213670, 2017). "Whether this finding reflects the progression of tumorigenesis or the mechanism of tumor initiation associated with Atad5 haploinsufficiency has not been determined." (PMID 21901109, 2011).
tumor (continued). "Collectively, our findings suggest that ATAD5 may be a novel tumor suppressor gene." (PMID 21901109, 2011). "ATAD5 gene is upregulated by activating E2F1, a key regulator of cell cycle progression, which promotes HBV replication and protects tumor cells from anticancer drugs." (PMID 38495502, 2024). "The mammalian ortholog of Elg1, ATAD5, is also a PCNA unloader, important for genome stability, and acts as a tumor-suppressing gene." (PMID 32371600, 2020). "The requirement for Elg1 in genome maintenance is conserved in higher eukaryotes, since mice with reduced expression of ATAD5 exhibit genome instability and have a high tumor incidence." (PMID 31114918, 2019). "Elg1/ATAD5 forms a replication factor C (RFC)-like complex with Rfc2-5, which is vital for genome stability, and, in mice and humans, appears to act as a tumour suppressor." (PMID 31149897, 2019). "Haploinsufficiency of certain genes may contribute to dysmorphic facial features, overgrowth and reduced cognitive capability (RNF135) or heart defects (ADAP2), whereas others might have tumor suppressive function, thus their deletion promote tumor development (SUZ12, ATAD5)." (PMID 34168676, 2021).
cancer (16 papers, 2011 to 2026). A tumor composed of atypical neoplastic, often pleomorphic cells that invade other tissues. "Deficiency of the elg1/Atad5 gene in yeast and mice leads to chromosome instability, whilst also predisposing mice to cancer, suggesting that the timely unloading of PCNA is critical for genome stability." (PMID 38141767, 2024). "ATAD5 expression is significantly higher in human cancers, such as HBV-associated HCC and various HCC cell lines, compared to normal liver cells." (PMID 34202146, 2021). "Additionally, somatic mutations of ATAD5 have been found in patients with several types of cancer and a genome-wide analysis indicated that the ATAD5 locus confers enhanced susceptibility to endometrial, breast, and ovarian cancers." (PMID 31844045, 2019). "The high incidence of cancer in the Atad5+/m mice, led us to hypothesize that somatic mutations of ATAD5 might be associated with human cancers." (PMID 21901109, 2011). "Moreover, given that Atad5 heterozygous mice are cancer-prone and that ATAD5 mutations have been detected in tumors of the breast, ovary and endometrium, we wondered whether ATAD5 deficiency could be exploited therapeutically." (PMID 32297953, 2020). "Furthermore, given our observation that haploinsufficiency for Atad5 in mice predisposes to tumorigenesis, it will also be important to determine whether germline variants of ATAD5 confer increased risk for cancer." (PMID 21901109, 2011). "Their high correlation to assays targeting STAT1 or ATAD5, which are important in cancer and immune disorders, is a valuable finding by a simple linear correlation analysis of MolData benchmark for drug repurposing." (PMID 35255958, 2022). "Most importantly, in a pilot screen of approximately 4,000 small molecules, the ATAD5-luciferase assay successfully identified three potential chemotherapeutic agents that offer improvements over conventional cancer drugs." (PMID 22653910, 2012). "Notably, the ATAD5/PRR11-AS1/SKP2 triplet exhibits favorable prognostic potential across multiple cancers and consistently outperforms individual gene markers in predicting 1-, 3-, and 5-year overall survival." (PMID 42242683, 2026). "Our findings warrant future investigations to explore the role of ATAD5 in other human cancers." (PMID 21901109, 2011). "Here we discuss the ATAD5-luciferase assay and expand upon the value of HTS in identifying other potential cancer drugs, focusing on cell-based assays that involve DNA damage or repair pathways." (PMID 22653910, 2012). "Cells lacking Elg1/ATAD5 exhibit genome instability that leads to cancer." (PMID 27373149, 2016). "One example of such an assay is the ATAD5-luciferase HTS assay, which identified three antioxidants that could kill cancer cells without inducing mutagenesis." (PMID 22653910, 2012).
ATAD5 also shares sentences with these, for which no sentence is quoted: adenocarcinoma (3 papers); adenoma (1); Cognitive impairment (1); colon cancer (1); developmental delay (1); Fanconi anemia (1); hamartoma (1); immune disorders (1); intellectual disabilities (1); neuroblastoma (1); pancreatic cancers (1).